ENSG00000207299
Synonyms: LOC124900309
Gene: Small nucleolar RNA gene on chromosome 11 (90,118,391 to 90,118,461, forward strand). Ensembl gene ENSG00000207299.
Gene Ontology:
Biological process: RNA processing
Cellular component: nucleolus
Homologues: Paralogues in human: SNORD56 (87% identical), SNORD56B (83% identical).